NSUN5 (NOP2/Sun RNA methyltransferase 5)
Diseases named in the same sentence as NSUN5 in open-access papers (continued):
Sharing a sentence is not in itself a finding about the gene and the disease.
glioma (continued). "Most significantly, we have shown that NSUN5 inactivation is a likely pathway used by glioma cells to overcome hostile stress conditions by restraining high energy-consuming global protein synthesis while stimulating the translation of adaptive proteins such as NQO1." (PMID 31428936, 2019). "Thus, we set out to demonstrate that NSUN5 is responsible for methylating C3782 28S rRNA in our glioma models." (PMID 31428936, 2019). "Upon efficient transfection of NSUN5, we studied the growth of glioma cells in vivo by performing intracerebral mouse xenotransplantation experiments using LN229 and A172 GFP-Luc cell lines, and quantified tumor growth over time by measuring luciferase activity." (PMID 31428936, 2019). "Interestingly, the value of NSUN5 hypermethylation as a predictor of better outcome was observed for low- and high-grade gliomas." (PMID 31428936, 2019). "Importantly, the impact of NSUN5 methylation on PFS is maintained when the glioma validation samples are divided into grades." (PMID 31428936, 2019). "In this setting, NSUN5 exhibits tumor-suppressor characteristics in vivo glioma models." (PMID 31428936, 2019). "Furthermore, we extended these assays to NSUN5 methylated LN229 glioma cells, where we have exogenously restored NSUN5 activity and thus depleted the NQO1 protein." (PMID 31428936, 2019). "Thus, the occurrence of NSUN5 methylation pinpoints glioma cells that are more sensitive to the cytotoxic effect of NQO1 substrates." (PMID 31428936, 2019). "Thus, all these results indicate that NSUN5 is the human C3782 28S rRNA methyltransferase and that epigenetic silencing of NSUN5 in glioma cells prevents the formation of this chemical modification in the rRNA transcript considered here." (PMID 31428936, 2019). "Interestingly, NSUN5 epigenetic inactivation also renders these gliomas sensitive to bioactivatable substrates of the stress-related enzyme NQO1." (PMID 31428936, 2019). "First, we demonstrated by western-blot analyses that the three studied glioma cell lines with NSUN5 hypermethylation (LN229, A172, and KS-1) showed high levels of NQO1, whereas minimal expression of NQO1 was observed in the three NSUN5 unmethylated cell lines (DBTRG-05MG, MO59 J, and CAS-1)." (PMID 31428936, 2019). "Therefore, targeting the regulation of NSUN5 expression in glioma patients to alter the tumor immune microenvironment and promote the body's immune response to tumor cells is expected to become a new strategy for glioma treatment." (PMID 41555554, 2026). "Therefore, NSUN5 may be a key factor influencing glioma invasiveness and prognosis and could serve as a potential therapeutic target." (PMID 41555554, 2026). "Therefore, highly expressed NSUN5 can be utilized to predict the prognosis of gliomas." (PMID 40469294, 2025). "Therefore, promoting NSUN5 expression has emerged as a novel therapeutic target for gliomas." (PMID 40469294, 2025). "Many studies have claimed that NSUN5 deficiency results in a non-methylated state at the C3782 position of the 28S rRNA, strengthening the survival adaptability of glioma cells under stress conditions, potentially worsening the survival and prognosis of patients with glioma." (PMID 37964279, 2023). "Moreover, by studying a different validation cohort, the authors could confirm and extend these results, by calculating a positive correlation between NSUN5 hypermethylation and progression-free survival in both low grade gliomas and in glioblastomas." (PMID 32316617, 2020). "Indeed, differential regulation of NSUN5 expression in various tissues was recently demonstrated to happen at epigenetic level, since methylation of the NSUN5 promoter was high in some glioma cell lines and primary tumors, but low in cervical and other malignancies." (PMID 31722427, 2019).
glioma (continued). "Most notably, the NSUN5-hypermethylated glioma cell lines LN229, A172 and KS-1 minimally expressed the NSUN5 RNA transcript and protein, as determined by quantitative real-time PCR and western blot, respectively." (PMID 31428936, 2019). "We found the 5′-end region of NSUN5 of the LN229, A172, and KS-1 glioma cell lines to be hypermethylated in comparison with normal brain white matter, whereas the DBTRG-05MG, CAS-1, and MO59 J cells were unmethylated." (PMID 31428936, 2019). "Conversely, the glioma cell lines unmethylated at the NSUN5 promoter (DBTRG-05MG, CAS-1, and MO59J) expressed NSUN5 RNA and protein." (PMID 31428936, 2019). "Additionally, NSUN5 inactivation sensitises gliomas to NQO1‐targeted treatments and is a marker of long‐term survival in glioma patients, highlighting its significance in cancer's epitranscriptomic regulation." (PMID 38797935, 2024). "The expression of NOP2, NSUN2, NSUN4, NSUN5, and NSUN7 were positively correlated in gliomas." (PMID 32974125, 2020). "Most importantly, the determination of the corresponding IC50 values, according to the SRB assay for cell viability, showed that NSUN5 hypermethylated glioma cells were significantly more sensitive to the DNQ and IB-DNQ drugs than the NSUN5 unmethylated glioma cell lines (z test, P < 0.0001)." (PMID 31428936, 2019). "Our findings are corroborated by another recent study, showing that C3782 was the only methylation site altered upon ectopic expression of NSUN5 in a NSUN5 lacking glioma cell line." (PMID 31722427, 2019). "To map NSUN5-dependent modified cytosine sites across the human transcriptome, we coupled bisulfite conversion of cellular RNA with next-generation sequencing (bsRNA-seq) in NSUN5-transfected LN229 glioma cells and empty-vector-transfected cells." (PMID 31428936, 2019). "Notably, the downregulation of NSUN5 in gliomas, resulting from CpG island hypermethylation at its promoter region, affects another key epitranscriptomic mechanism: the absence of NSUN5 leads to hypomethylation (m5C) at position C3782 of human 28S rRNA." (PMID 40002173, 2025). "All five RNA:m5C methyltransferase genes, NOP2, NSUN4, NSUN5, NSUN6, and NSUN7, were differentially expressed between normal brain tissues, low grade and high grade glioma tissues." (PMID 32974125, 2020).
colorectal cancer (13 papers, 2020 to 2026). A primary or metastatic malignant neoplasm that affects the colon or rectum. "NSUN5 is significantly more expressed in colorectal cancer, and studies have shown that knocking out NSUN5 in colorectal cancer cell lines causes cell cycle blockade by inhibiting cyclin-dependent kinase (CDKs) signaling, significantly inhibiting cell proliferation." (PMID 37168511, 2023). "NSUN5 shows abnormal expression in various cancers, including gastric cancer, clear cell renal carcinoma, colorectal cancer, liver cancer, and head and neck squamous cell carcinoma, playing a key role in tumor initiation and progression." (PMID 41555554, 2026). "Research has shown that in colorectal cancer patients and mouse models, the mRNA levels of NSUN5 and YBX1, as well as the total RNA m5C levels, are elevated." (PMID 40370440, 2025). "NSUN5 is markedly upregulated in head and neck squamous cell carcinoma and acts as a promoter of colorectal cancer by inducing cell cycle arrest." (PMID 41536427, 2025). "Co-culture experiments indicate that colorectal cancer cells promote the expression of NSUN5 and YBX1 in immune cells, leading to increased m5C levels in these cells." (PMID 40370440, 2025). "Multiple studies have been performed that NSUN5 is overexpressed in various types of cancers including gastric cancer, hepatocellular cancer, renal cancer, colorectal cancer." (PMID 41536427, 2025). "In colorectal cancer, highly expressed NSUN5 promotes tumor cell proliferation by regulating the cell cycle." (PMID 40370440, 2025). "Overexpression of NSUN5 is associated with tumorigenesis in HCC and colorectal cancer (CRC) patients, while NSUN5 deficiency causes a reduction in total protein synthesis, thus impairing cell proliferation." (PMID 37325635, 2023). "Taken together, these results suggested that DKC1, CSE1L and NSUN5 were dramatically overexpressed while FLNA was significantly downregulated in colorectal cancer." (PMID 36319976, 2022). "High expression of NSUN5 has been reported to promote cell proliferation via cell cycle regulation in colorectal cancer." (PMID 34512654, 2021). "NSUN5 may regulate colorectal cancer cell proliferation through the Retinoblastoma (Rb)-cyclin-dependent kinase (CDK) pathway." (PMID 40370440, 2025). "Additionally, NSUN5 is upregulated in colorectal cancer tissues and cells, and NSUN5 knockout mice exhibit significantly reduced cell proliferation and cell cycle arrest." (PMID 40370440, 2025). "GSEA suggested that NSUN5 may promote the proliferation of colorectal cancer cells through the Rb-CDK signal transduction pathway." (PMID 35562754, 2022). "Our results suggest that NSUN5 plays a protumorigenic role in GBM cells, which is in line with the strong association between the elevated NSUN5 expression and shorter overall and disease‐free survival of GBM patients and in accordance with the studies in colorectal cancer and cervical cancer." (PMID 37057706, 2023). "NSUN5 is significantly upregulated in head and neck squamous cell carcinoma (HNSCC) and acts as a promoter of colorectal cancer (CRC) by triggering cell cycle arrest.." (PMID 35562754, 2022). "Among them, the P value of the NSUN5 and ALYREF genes in colorectal cancer, liver cancer, and GC is less than 0.05, and the NSUN6 gene also has significant differences in colorectal cancer, liver cancer, and PC." (PMID 33365328, 2020).
glioblastoma (12 papers, 2019 to 2025). The most malignant astrocytic tumor (WHO grade IV). "In glioblastoma, NSUN5 loss generates an unmethylated status at the C3782 position of 28S rRNA, resulting in an anti-tumor effect." (PMID 41536427, 2025). "Lastly, NSUN5 expression has been found to correlate with poor survival in glioblastoma and NSUN7 high expression is associated to shorter survival in low-grade gliomas." (PMID 33461542, 2021). "In somatic contexts, rare mutations in NSUN5 have been reported in various cancers, including hepatocellular carcinoma and glioblastoma, which can alter RNA methylation patterns and downstream signaling pathways, promoting tumor progression or affecting tumor suppressor functions." (PMID 41536427, 2025). "NSUN5 mRNA expression is strongly associated with poor survival in glioblastoma patients." (PMID 33461542, 2021). "Using H2O2 in the medium to produce oxidative stress, we found that the three glioblastoma cell lines harboring NSUN5 epigenetic loss (LN229, A172, and KS1) show overall lower global protein synthesis than the three NSUN5 unmethylated cell lines (DBTRG-05MG, MO59 J and CAS-1)." (PMID 31428936, 2019). "Knocking down NSUN5 reduced protein synthesis, cell proliferation, spheroid formation, migration, and resistance to temozolomide in glioblastoma cell lines." (PMID 41462962, 2025). "We next looked at bsRNA-seq data from LN229 human glioblastoma cells, where NSUN5 was either epigenetically silenced (control) or overexpressed by lentiviral transduction (OE)." (PMID 38986569, 2024). "For example, we found that high NSUN5 expression levels in glioblastoma (GBM) are correlated with poor prognosis, in agreement with a recent study." (PMID 32375858, 2020). "To this end, we analyzed the effect of the restoration of NSUN5 expression in the NSUN5-hypermethylated glioblastoma cell lines LN229 and A172." (PMID 31428936, 2019). "NSUN5 methylates cytosine 3782 of 28S rRNA in glioblastoma cells." (PMID 41462962, 2025). "Elevated NSUN5 expression is closely related to poor survival in patients with glioblastoma." (PMID 41462962, 2025). "The expression level of NSUN5 is correlated with poor survival in glioblastoma patients." (PMID 36360287, 2022). "In glioblastoma (GBM), NSUN5 drove tumorigenesis by catalyzing m5C methylation at the C3782 site of 28S rRNA, thereby enhancing protein translation." (PMID 41413017, 2025). "In glioblastoma (GBM), NSUN5 enhances protein synthesis necessary for tumor progression, thereby promoting malignancy." (PMID 41256854, 2025). "We next performed comparative bisulfite sequencing of multiple clones of the 28S rRNA extracted from the NSUN5 unmethylated glioblastoma cell lines DBTRG-05MG, MO59J, and CAS-1, and the NSUN5 hypermethylated and transcriptionally silenced LN229, A172, and KS-1 glioblastoma cell lines." (PMID 31428936, 2019). "We also studied the expression of RNA:m5C methyltransferases in glioblastomas (GBM) stratified by IDH mutant status, and findings indicated that NSUN5, NSUN6, and NSUN7 were still differentially expressed." (PMID 32974125, 2020). "In glioblastoma (GBM), NSUN2, DNMT3B, NSUN5, TRDMT1, ALKBH1, and HNRNPC were selected." (PMID 40565233, 2025).
head and neck squamous cell carcinoma (6 papers, 2021 to 2026). A squamous cell carcinoma that arises from any of the following anatomic sites: lip and oral cavity, nasal cavity, paranasal sinuses, pharynx, larynx, and salivary glands. "NSUN4, NSUN5, NSUN6 and NSUN7 are associated with cancer development in HCC, head and neck squamous cell carcinoma (HNSCC), pancreatic cancer and glioma 29, 114-116." (PMID 34512153, 2021). "In head and neck squamous cell carcinoma (HNSC), the presence of HNRNPC, DNMT1, DNMT3A, ZC3H13, NSUN5, and IGF2BP2 highlights potential cross-talk between DNA and RNA methylation in immune modulation." (PMID 40565233, 2025).
colon cancer (4 papers, 2021 to 2025). "We found that Gsn and Spg20 mRNA expression was significantly lower, and NSUN5 mRNA expression was significantly higher in colon tumor tissues than in normal tissues." (PMID 39962271, 2025). "The mRNA levels of DKC1, CSE1L and NSUN5 were higher in the colon cancer tissues than in the paired adjacent normal tissues, while the level of FLNA was lower (p < 0.05)." (PMID 36319976, 2022). "The high expression of NSUN5 can promote the proliferation of colon cancer cells, and the high expression of NOP2 can promote the metastasis of prostate cancer and the proliferation of liver cancer cells." (PMID 34631874, 2021).
hepatocellular carcinoma (4 papers, 2025). A malignant tumor that arises from hepatocytes. "Elevated expression of NSUN5 is associated with reduced relapse-free and overall survival rates and predicts poor prognosis in hepatocellular carcinoma." (PMID 40370440, 2025).
liver cancer (4 papers, 2020 to 2026). An epithelial or non-epithelial malignant neoplasm that arises from the liver. "To further substantiate these findings in vivo, we performed IHC staining on liver cancer specimens induced in wild‐type and Nsun5‐KO mice, which revealed a significant reduction in Smad3 content in Nsun5−/− mice, consistent with our experimental observations." (PMID 39531371, 2025).
prostate carcinoma (4 papers, 2021 to 2025). A carcinoma that arises from epithelial cells of the prostate gland. "NSUN5 is closely associated with abnormal lipid metabolism in prostate cancer." (PMID 40809690, 2025). "NSUN5 promoted prostate cancer proliferation and migration through the PI3K–AKT pathway, induced macrophage polarization into a pro-tumor phenotype, and promoted the formation of an inhibitory tumor microenvironment." (PMID 41462962, 2025). "NSUN5 is significantly overexpressed in prostate cancer tissues and positively correlated with advanced disease stages and poor prognosis." (PMID 41462962, 2025). "In the mechanism of prostate cancer, CDK13 interacts with NSUN5, promoting its phosphorylation at the Ser327 site." (PMID 41462962, 2025). "Conversely, phosphorylated NSUN5 catalyzes m5C modification of ACC1 mRNA, which binds to ALYREF to enhance its stability and nuclear output, promoting ACC1 expression and lipid deposition in prostate cancer cells." (PMID 41462962, 2025).
Williams-Beuren syndrome (4 papers, 2019 to 2025). "Haploinsufficiency of the NSUN5 gene in fibroblasts from William Beuren syndrome patients causes partial loss of this modification." (PMID 31722427, 2019). "Notably, the human Nsun5 locus lies within a genomic region frequently deleted in Williams-Beuren syndrome, linking NSUN5 loss to multisystem developmental abnormalities." (PMID 41148823, 2025).
breast carcinoma (3 papers, 2022 to 2025). "Comparison of the expression patterns of the m5C machinery across breast cancer subtypes revealed that the m5C methyltransferase NSUN5 and the readers ALYREF, YBX1, and YBX2 were overexpressed in the basal subtype relative to normal tissue." (PMID 40918643, 2025). "Six breast cancer differentially localized proteins were got: CCNT1, NSUN5, PRPF4, RECQL4, UTP6, ZNF500." (PMID 39095659, 2024). "Expression of NSUN1, NSUN2, NSUN5, DNMT1, DNMT3A, DNMT3B, and ALYREF was significantly increased, but DNMT2 and TET2 expression was markedly decreased in breast cancer tissues when compared with normal breast tissues." (PMID 35812757, 2022). "Based on the results of survival analysis (p < 0.05), it was found that the results of UTP6, NSUN5 and RECQL4 proteins were more relevant to the prognosis of breast cancer, while the results of CCNT1 and PRPF4 were not." (PMID 39095659, 2024).
renal carcinoma (3 papers, 2021 to 2025). A carcinoma arising from the epithelium of the renal parenchyma or the renal pelvis. "NSUN5 is upregulated in ccRCC tissues and renal cancer cell lines and is associated with poorer OS and progression-free survival (PFS)." (PMID 41462962, 2025). "As migration and invasion are characteristics of renal cancer, wound healing and transwell assays were used to validate the effects of NSUN5 on ccRCC cells." (PMID 37263638, 2023). "NOP2, NSUN2, and NSUN5 mRNA were significantly upregulated in renal cell carcinoma cell lines (786-O, Caki-1) compared to a human tubular epithelial immortalized cell line (HK-2), while NSUN4 was downregulated in the renal carcinoma cell lines." (PMID 41462962, 2025).
cognitive disorder (2 papers, 2019). A disease affects cognitive processes. "Nsun5-KO mice and heterozygous Nsun5 mice show the cognitive disorder phenotype, which is companied by the CC agenesis and hypomyelination (in this study)." (PMID 31174389, 2019). "Since recent studies found cognitive deficits in Nsun5 knockout mice and WBS patients show neural abnormalities, NSUN5 might contribute to the pathology of WBS." (PMID 31722427, 2019).
Tetralogy of Fallot (2 papers, 2021 to 2022). A congenital cardiac malformation comprising pulmonary stenosis, overriding aorta, ventricular septum defect, and right ventricular hypertrophy. "NSUN5, encoding a cytosine-5 RNA methyltransferase and located in the 7q11.23 locus, is a candidate gene for tetralogy of Fallot (TOF)." (PMID 33968922, 2021). "Moreover, in the cardiovascular system, NSUN5-mediated m5C modification is essential for maintaining the expression of Tpm1, which is an essential gene for normal cardiac outflow tract (OFT) morphogenesis, suggesting the involvement of NSUN5 in the tetralogy of Fallot (TOF)." (PMID 35562754, 2022).
cholangiocarcinoma (1 paper, 2025). A carcinoma that arises from the intrahepatic biliary tree (intrahepatic cholangiocarcinoma) or from the junction, or adjacent to the junction, of the right and left hepatic ducts (hilar cholangiocarcinoma). "NSUN5 overexpression enhanced the growth and metastasis of cholangiocarcinoma cells by positive regulation of glutaminase expression." (PMID 41462962, 2025). "In cholangiocarcinoma, NSUN5-mediated m5C modification is located at the 137 C site of the glutaminase mRNA sequence, stabilizing glutaminase mRNA and leading to the accumulation of intracellular glutaminase." (PMID 41462962, 2025).